RNU6-991P (RNA, U6 small nuclear 991, pseudogene)
Gene: Small nuclear RNA gene on chromosome 1 (8,292,157 to 8,292,263, reverse strand). Ensembl gene ENSG00000251977.
Homologues: Orthologues: chimpanzee U6 (97% identical), macaque U6 (86% identical), rabbit U6 (64% identical). Paralogues in human: RNU6-106P (79% identical), RNU6-12P (77% identical), RNU6-13P (77% identical), RNU6-14P (77% identical), RNU6-16P (77% identical), RNU6-32P (77% identical), RNU6-338P (77% identical), RNU6-7 (77% identical), RNU6-799P (77% identical), RNU6-8 (77% identical), RNU6-1 (76% identical), RNU6-1011P (76% identical), and 1285 more.